CD4 (CD4 molecule)
Diseases named in the same sentence as CD4 in open-access papers (continued):
Sharing a sentence is not in itself a finding about the gene and the disease.
infection (continued). "Among influenza A/H3N2-infected patients, stimulation with H1N1 elicited a significant increase in IL2+, TNFα+ and polyfunctional CD4+ T-cells, as seen with stimulation with H3N2 suggesting that natural infection does result in heterosubtypic immunity." (PMID 32572168, 2020). "The Q309R variant associated with ribavirin resistance was present in 12 individuals with HCV mono-infection, 8 HIV/HCV co-infected individuals with CD4 <350 cells/mm3, and 12 HIV/HCV co-infected individuals with CD4 ≥350 cells/mm3." (PMID 32750098, 2020). "Using this more‐focused approach, IFN‐γ‐producing CD4+ T cells were evident in the spleen at day 3 of infection, but by day 8, the YFP+ CD4+ T cells were diminished, and by day 11, the remaining YFP+ CD4+ cells in the spleen were also CD4high." (PMID 33282291, 2020). "Infection of naïve fish with SAV resulted in a statistically significant (p ≤ 0.05) increase in IgM+ and CD4+ cells in PBLs in comparison to all other treatment groups." (PMID 33276596, 2020). "Both CD4 and CD8 T cells showed similar frequency in WT and IL16 KO mice after MHV68 infection, however, IFN-γ-expressing Th1 subset of CD4 T cells and CD44+ activated CD4 T cells were dramatically increased in IL16 KO mice as compared to WT mice." (PMID 32735617, 2020). "It was demonstrated that the CD4+ T cell and CD8+ T cell amounts were strictly correlated to infection gravity and prognosis: the lower the amounts of T cell, CD4+ T cell, and CD8+ T cell at the time of hospitalization, the more negative the prognosis." (PMID 32640747, 2020). "NK cells depletion led to the impaired functional capability of memory CD4+ and CD8+T cells especially in IFN-γ production during specific antigen re-stimulation in vitro and in vivo during secondary infection." (PMID 32626664, 2020). "Characterization of SARS-CoV-specific memory T cells from recovered individuals 4 years after infection indicated that the majority of memory CD8+ T cells produced IFN-γ, whereas memory CD4+ T cells produced IFN-γ, IL-2, or TNF-α." (PMID 33013871, 2020). "With these facts in mind, we selected six immunodominant CD4 and CD8 T cell epitopes of Mtb expressed during latent, acute, and chronic stages of infection and engineered a multi-epitope-based DNA vaccine (C6)." (PMID 32942991, 2020). "In humans, it is well established that patients with chronic hepatitis viruses and/or HIV infection have an impaired adaptive immunity with dysfunctional CD4+ and CD8+ T cells contributing to the inability to clear the infection." (PMID 33133084, 2020). "Since the gastrointestinal track is a major reservoir of CD4+TRM, it is important to understand their role in protective immunity against S. Typhi and other enteric pathogens at their preferred site of natural infection." (PMID 32098623, 2020). "In the following, we will first address the roles of HCV-specific B cells/neutralizing antibodies, as well as CD4+ and CD8+ T cells, since all of these were demonstrated to have important roles in infection outcome." (PMID 32781731, 2020). "PD-L1-/- mice were either injected with anti-CD8β or anti-CD4 depleting mAbs or PBS prior to infection with Py, and 9, 12, and 15 days post-infection, mice received anti-LAG-3 or control isotype Abs." (PMID 33519801, 2020). "All investigated cell types, encompassing macrophages as well as CD4+ and CD8+ T cells, were found to produce TNF-α 8 days post-infection." (PMID 32069329, 2020). "In the intestine BALB/c mice the infection with Y increased Ifng / Il6 expression, but with VFRA there was an increased in Cd4 / Tnf which was protective." (PMID 32925918, 2020). "With the exception of the acute phase, all the other infection phases showed that, at ALP approx. >80 IU/L, the CD4+ count cell count was above average." (PMID 32190387, 2020). "High levels of CD4+ and CD8+ T cells formed prior to infection allow for effective warfare against Plasmodium infection." (PMID 32751598, 2020).
infection (continued). "The IFN-γ production by restimulated PBMCs was correlated with the infection dose and predominantly brought about by CD3+ CD4- CD8+ T lymphocytes." (PMID 33324583, 2020). "In the spleens of IM-immunized mice, the frequencies of CD4+ T cells expressing IL-17A, IFN-γ, IL-10 and TNF-α were found similar when compared to controls, both before and after infection." (PMID 32040500, 2020). "In Phase 3 of infection, fewer T cells were present in the brains and CD8+ and CD4+ T cells produced the majority of IFN-γ." (PMID 31963302, 2020). "Many of the N/CHR mutations we identified also enhanced entry into cells bearing human CD4 and CCR5 receptors, but the magnitude of this effect was smaller than during infection of cells bearing macaque receptors." (PMID 32098152, 2020). "Much like memory CD8+ T cells, CD4+ T cells form long-lived circulating (TCM, TEM) and tissue-resident (TRM) memory populations, which establish upon the resolution of infection." (PMID 32858901, 2020). "Depletion of both subsets did result in higher viral titers, showing that both CD4+ and CD8+ T cells are necessary for clearing the primary infection in the lungs." (PMID 32423043, 2020). "We also conclude that, at the level of infection tested, E. maxima induces a systemic downregulation of CD8+ lymphocytes, whereas HS and E. maxima infection induce upregulation of CD4+ lymphocytes." (PMID 32612102, 2020). "After viral infection, the activated immune system would not only directly induce antiviral cellular and humoural immune responses but also develop memory CD4+ and CD8+ T cell subsets as a preparation for secondary infection." (PMID 33145962, 2020). "According to the results of flow cytometry from spleen, mice in vaccine groups showed higher percentages of CD4+ and CD8+ T cells than those in the normal and control groups at 8th week post-infection." (PMID 32176727, 2020). "HCV elimination coincides with strong and sustained multi-specific CD4+ and CD8+ T cell immunity which remains detectable after the spontaneous resolution of infection." (PMID 32722372, 2020). "They found that CD4-IgG2 bound gp120 with high affinity and was much more potent than sCD4 to inhibit HIV-1 fusion and infection." (PMID 32523582, 2020). "During the later stage of infection, HIV primarily targets HIV-specific CD4+ T cells during the CD4+ T cell proliferation and transition phase from naïve to effector and memory T cells, becoming HIV latent reservoirs." (PMID 32858917, 2020). "Rarely reported Enterovirus A infections as well as infections with zoonotic potential types were almost exclusively detected in HIV-positive individuals with an impaired immune system, as indicated by a low CD4+ T cell count." (PMID 32079128, 2020). "The early-transmitting HIV-1 virions that succeed to establish a productive infection in vivo are CCR5 tropic and the ability to infect the α4β7 integrin+CD4+ CCR5+ T cell population in the mucosa." (PMID 32876566, 2020). "This method first estimates the distribution of diagnosis delays (i.e., the time from infection to diagnosis), and then estimates the incidence of HIV from the depletion of CD4+ T-cells." (PMID 31964392, 2020). "Within the CD4+ T-cell compartment, memory CCR6+ Th17 cells were found to be preferentially infected very early following infection and harbor high levels of replication-competent HIV DNA compared to CCR6− T cells (40, 62, –, 64)." (PMID 32967958, 2020). "Flow cytometry was used to identify relative frequencies of CD4, CD8, and γδ T cells present in the airways at this timepoint after infection." (PMID 32780814, 2020). "The proportion of CD3+CD4+ and CD3+CD8+ T cells in the mouse spleen was measured with flow cytometry analysis before and after infection." (PMID 32334611, 2020). "We observed that both CD4+ and CD8+ T cells produce LT-α in response to Mtb infection at 6 and 8 days post-infection." (PMID 32069329, 2020).
infection (continued). "CD4+ T cells from C57BL/6 as well as from BALB/c mice express huge amounts of IFNγ and lower amounts of TNFα in the infection with R. typhi with a peak response around day 7 postinfection, which is similar to the CD8+ T cell response." (PMID 33091016, 2020). "In this manuscript we show that exposure to TCS resulted in the reduction of total CD4+ and CD8+ T cell responses as well as activated (CD44+) T cells responding to infection at the peak of the T cell response (10 dpi)." (PMID 33373420, 2020). "Murine studies have presented with the evidence that both CD4+ and CD8+ T cells infiltrate CHIKV-infected tissues during the course of infection." (PMID 32411133, 2020). "CD4+ and CD8+ T cells are important during acute phase of infection and in clearance of chronic infection, respectively." (PMID 32793184, 2020). "Consistent with the systemic alarmin function of HA fragments as a DAMP, we observed a greatly decreased induction of CD4+ cells expressing Tbet, GATA3, RORγt, INFγ, and1 IL-17 in Cemip−/− mice following infection." (PMID 31914398, 2020). "To distinguish between preferential infection versus remodeling, we recently implemented the bioinformatics approach SLIDE on HIV-infected tonsillar CD4+ T cells phenotyped with a 38-parameter CyTOF panel." (PMID 32452381, 2020). "HIV capture to DCs by binding to CD4 and CCR5 and, depending on expression of CLRs, can mediate infection through fusion with the cell membrane." (PMID 32824563, 2020). "Flow cytometry measurements of CD45+CD3+CD4+ and CD45+CD3+CD8+ frequencies over the course of infection correlated with those measured by Seq-Well." (PMID 32251406, 2020). "Following infection, we observed a substantial expansion of IFN-γ+ CD4 effector T cells in both control and Bach2fl/flCd4Cre mice (left)." (PMID 31937752, 2020). "On day 28 after infection this population had contracted, although in some individuals, BAL CD4+ T cells continued to rise in frequency during convalescence." (PMID 31815739, 2020). "We co-cultured NK cells from HIV− and HIV+ donors with autologous CD4 T cells infected in vitro with the HIV strain Q23-FL; infection levels in CD4 T cells after co-culture were similar between HIV+ and HIV− donors." (PMID 32477342, 2020). "The total numbers of T cells, CD4+ T cells, and CD8+ T cells were markedly higher in the ubi1Δ strain-infected mouse lungs than in the WT-infected ones at all infection stages." (PMID 33224112, 2020). "IL-7 expression level is upregulated in response to CD4+ T cell depletion during HIV-1-infection, promoting proliferation of HIV-1-infected CD4+ T cells." (PMID 31910871, 2020). "CD4 T cells are also the chief source of IFN-γ that is produced in an antigen independent, IL-18—dependent manner during infection with Salmonella." (PMID 32269573, 2020). "This evidence suggests that TIM3 can regulate CD4 and CD8 T cell responses in the context of infection." (PMID 32714317, 2020). "The significantly increased infiltration of CD4 T cells and B cells in LUAD patients with high expression levels of ACE2 and TMPRSS2 may cause an imbalance in immune regulation, making patients more susceptible to SARS-CoV-2 invasion, and the inflammatory response after infection is aggravated." (PMID 33195212, 2020). "Infection with Plasmodium chabaudichabaudi AS (PccAS) reduced EAE severity, possibly due to the induction of regulatory CD4+ T cells (Treg) and the production of IL-10 and TGF-β." (PMID 32265335, 2020). "Th1 (CD3+CD4+IFN-γ+) and Th2 (CD3+CD4+IL-4+) T cells in the liver were analyzed by flow cytometry at 8 weeks post-infection." (PMID 32503644, 2020). "Activated primary CD4 T cells were infected with single-round CXCR4-tropic HIV-1 pseudoviruses, GFP− cells were sort-purified 4 days post infection, then each of the four genes were knocked down using pLKO.1-shRNA lentiviral vectors." (PMID 33270809, 2020).
infection (continued). "How to nest the with-host information on viral loads and CD4 level into between-host modelling and simulations and accurately estimating HIV new infections becomes challenging." (PMID 32532238, 2020). "CD4+ T cells infiltrate the lower respiratory mucosa following RSV challenge and peak 10 days after infection." (PMID 31815739, 2020). "Levels of human CD4 T-cells in HIV-infected h-BLT mice, dramatically decreased during the course of infection, and maintained levels similar to those seen in HIV+ h-BLT mice (HEC alone)." (PMID 33321835, 2020). "Vaccination or infection with Salmonella Typhi led to the induction of MF CD8+ and CD4+ T-cell responses, that, in case of MF CD8+ T cells in PBMC, were demonstrated to correlate with disease outcome." (PMID 33584671, 2020). "To get an overall view of the infection profile of all infected immune cells, i.e. DCs, macrophages and CD4+ T cells, we pooled the data, analyzed, and found that the C-HIV and CI-HIV gave a significant fold increase in infection compared to F-HIV." (PMID 32876566, 2020). "Generally, the F3 vaccine induced the most potent CD4+ Th1 and CD8+ T cell responses before infection, while the F1F3 chimera was more efficient after challenge." (PMID 31024556, 2019). "Further assays and analyses revealed that CD34+CD7+CXCR4+ cells can be quickly depleted as early as 1 week after infection of the subset, and this was accompanied by the emergence of rare CD34+CD7+CD4+ cells." (PMID 30761146, 2019). "Incoming Vpr induced a significant depletion of CTIP2 in primary CD4+ T cells, suggesting that Vpr produced in cells upon HIV-1 replication and Vpr delivered by the virions upon infection reduce CTIP2 expression." (PMID 31511615, 2019). "The expression of the analyzed surface markers differed between the DC subsets upon infection, with the highest expression of CD80 and PD-L2 on the CD4+ DC subset." (PMID 31134074, 2019). "Co‐expression of both PD‐1 and Tim‐3 exhaustion markers on CD4+ and CD8+ SP T cells was significantly more common in chronic infection than either in past infection or in healthy controls (P < 0.05)." (PMID 30972915, 2019). "With restoration of absolute CD4+ T cell levels, IL-7 in the serum decreases and IL-7 mediated STAT-5 phosphorylation, which is elevated in memory CD4+ T cells in untreated infection, is normalized." (PMID 31507594, 2019). "(B) RhIV RNA levels (log10 copies /μg total RNA, upper row) and CD4+ T-cell numbers (% of CD3+ cells, lower row) in A1Ifnar-/- mouse tissues following infection with RhIVCH505." (PMID 31644426, 2019). "The size of the HIV reservoir depends on several factors, including the time interval between the infection and the initiation of ART, the CD4/CD8 ratio, and the level of inflammation (even in patients on ART)." (PMID 31921023, 2019). "Specifically, CD4+ T cells were incubated for 24 h with Debio 1143 together HIV-1-GFP and levels of infection were quantified by FACS." (PMID 30716099, 2019). "Similar control of IL-2 production from CD4 and CD8 T cells by CD70-dependent signals has been found in other infection models." (PMID 31412088, 2019). "In barrier tissues, like the lung, gut, and skin, CD4+ and CD8+ T cells take up residence following an infection." (PMID 31635220, 2019). "In this study, we compared the migration of naive and effector CD4+ and CD8+ T cells across a human in vitro model of the BCSFB based on HIBCPP cells following E-30 infection." (PMID 31752904, 2019). "At nine weeks post-infection, in peripheral blood of HIV-1 infected NSG-cmah−/− mice, the decreased proportion of CD3+ cells and specifically CD4+CD45RO+ effector memory cells with increased number of monocytes CD14+ were found." (PMID 30616506, 2019). "Significant differences in the Th subset dominance and distribution of the CD4 T cell responses in BALB/c and C57Bl/6 mice has been observed during infections [e.g., Leishmania, etc.]." (PMID 31632414, 2019).
infection (continued). "Mice challenged with M.tb 4 weeks after MIP i.n. vaccination, showed higher percentage of CD4+ and CD8+ T-cells in the airway luminal compartment (as observed in “before infection study”)." (PMID 31681272, 2019). "While these CD4+ T cells were rather consistent between the infection groups, PRRSV-2 vaccination or infection clearly resulted in a shift in the composition of T cells." (PMID 31470568, 2019). "In 2016, a new model incorporating CD4 at or after diagnosis, but before ART, was introduced in the United States to estimate HIV incidence, prevalence, and undiagnosed infections." (PMID 30892272, 2019). "Assessment of the persistence of TRM cells in the respiratory tissue revealed a high number of CD69+CD4+ TRM cells in the lungs and nasal tissue 7 days after secondary infection with B. pertussis." (PMID 30866771, 2019). "Given that amounts of CD4 and CD8 T cells in the elderly mice were diminished before the infection, the lower numbers of lymphoid populations infiltrating ears are likely reflective of the reduced availability of T cells in the blood circulation." (PMID 31417558, 2019). "At day 8 post-infection, we also observed some significant differences in the number of CD3+CD4+ T cells that infiltrates the cornea of B6 mice infected with virulent and less-virulent strains." (PMID 31367214, 2019). "The most marked differences from control were found in CD4−CD8+ and CD4+CD8+ (and partly also in CD3−8+ and γδ+8+) subsets of all immunized groups 7 days after infection." (PMID 31447829, 2019). "At 18-weeks post-infection, during the chronic infection phase, we used fluorescence-activated cell sorting (FACS) to isolate CD4+ T cells, CD8+ T cells, B cells, and monocytes from blood of uninfected cats and infected cats." (PMID 31500260, 2019). "Together, these studies demonstrate that ZIKV actively infects immunocompetent mice, generating a robust and functional CD4 and CD8 T cell response to infection." (PMID 31382545, 2019). "When accompanied by infection or inflammation, IL-6, and TGF-β initiate the differentiation of the initial CD4+ T cells into Th17 cells, thereby inducing chronic inflammatory response dominated by Th17 cells." (PMID 31757053, 2019). "At 12 weeks, the percentage of T2-type CD4+ T cells was significantly higher in HDG than in LDG and MDG (p = 0.0048; p < 0.001), and the percentage of T2-type cells increased with the dose of infection." (PMID 31873157, 2019). "As suspected, the reporter activity upon infection with MUT1 and MUT2 viruses of HeLa-CD4 cells carrying either WT or MUT LTRs was indifferent to the presence of 100 nM dCA." (PMID 31266880, 2019). "During acute HCV infection, DCs of the host should interact with the viral proteins to contribute the CD4+T and CD8+T cell responses for clearance or persistence of infection." (PMID 30909456, 2019). "Both CD4+ (helper) and CD8+ (cytotoxic) T cells play a critical role in regulating the outcome of infection with African trypanosomes." (PMID 31824512, 2019). "As a note of caution, HIV-specific CD4+ T cells are often compared to CMV-specific CD4+ T cells in terms of function and phenotype, despite major differences in the course of infection and viral replication kinetics." (PMID 31379821, 2019). "Total cell numbers of T cells, CD4+ and CD8+ T cells increased at 5 to 14 days post-infection in the peritoneal cavity." (PMID 31191534, 2019). "This study provides the foundation for further dissection of the H-2b-restricted CD4+ T cell response to ZIKV in various mouse models, including pregnant mice infected via systemic and mucosal routes in both natural infection and vaccination contexts." (PMID 30677097, 2019). "(A) FACS analysis of CD4 and CD8 expression on T-cells (gated on CD3+ cells) in three A1Ifnar-/- mice prior to RhIV infection (upper row) and 3 days after RhIVCH505 infection (lower row)." (PMID 31644426, 2019).